KRAS (KRas proto-oncogene, GTPase)
Diseases named in the same sentence as KRAS in open-access papers (continued):
Sharing a sentence is not in itself a finding about the gene and the disease.
cancer (continued). "Increased HKDC1 levels were further explained by a formation of a negative feedback loop to maintain high levels of glycolysis in the absence of KRAS signaling, a common feature of cancer cells." (PMID 28039486, 2017). "Mechanistically, we showed that MYC, a transcriptional factor involved in many cancers and a well‐known substrate of MAPK/ERK, facilitates IR‐induced DSB repair through regulation of HRR in KRAS‐mutant cells." (PMID 28173629, 2017). "Although targeting KRAS effector pathways has been suggested as a therapeutic alternative, there are no approved targeted therapies for the treatment of KRAS-mutant (KRASMUT) cancers." (PMID 28978051, 2017). "Forty-seven human cancer cell lines were treated with the CQ derivative Lys01 or shRNA to remove autophagic machinery components such as ATG7, revealing that KRAS-mutated cells are no more dependent on autophagy than their wild-type counterparts." (PMID 28316954, 2017). "Several malignant tumours have recently achieved personalized cancer treatment in clinical practice, such as anti-HER2 antibody for HER2-positive breast cancer, anti-EGFR therapy for KRAS wild-type colon cancer, and BRAF inhibitor for BRAF mutant melanoma." (PMID 28548943, 2017). "However, in other contexts, if KRAS and PIK3CA or EGFR and PIK3CA were tested, then testing for only two genes would be more expensive than the cancer panel." (PMID 28196074, 2017). "Our rationale for choosing these modules as relevant to the KRAS pathway in cancer was as follows: it has been demonstrated that MYC integrates RAS and PI3K signals and that both under- and overexpression of MYC can lead to cancer cell death." (PMID 28152508, 2017). "Raf or MEK inhibition yields good responses in some BRAF-mutant or KRAS-mutant cancers, but some patients have not been found to benefit from a single-target therapeutic approach." (PMID 29262632, 2017). "Notably, Poloppin sensitivity persists in cancer cells resistant to an ATP-competitive PLK1 inhibitor, and Poloppin sensitizes mutant KRAS-expressing cells to clinically used inhibitors of the MET tyrosine kinase, opening opportunities for combination therapy." (PMID 28807782, 2017). "Neither KRAS activation nor reduction of NKX2.1 alone is sufficient for carcinoma development or mucin production, indicating context specific crosstalk between these two genes." (PMID 29267283, 2017). "Whereas down‐regulation or loss of function of RABEX5 in human cancers has not been reported, we found that OTUB1 expression is commonly up‐regulated in a substantial subset of NSCLCs harboring wt KRAS." (PMID 26881969, 2016). "Intriguingly, the combination of BI-2536 and fasudil at low doses led to a more robust reduction of cell viability than either single agent alone in KRAS-mutant, but not wild-type, cancer cells." (PMID 27193833, 2016). "The role of autophagy in cancer is extremely complex and while it appears clear that PDAC cells depend on autophagy for growth, the role of oncogenic KRAS in this dependence remains unclear." (PMID 27096871, 2016).
cancer (continued). "No targeted therapies for KRAS mutant cancers are approved, because KRAS itself has proven difficult to target directly with small molecules." (PMID 27014419, 2016). "Considering that small number patients were included and anti-cancer treatments after surgery could not be analyzed in this study, however, further studies with large population are still needed to reveal the relationship between KRAS mutation and prognosis in patients with A-AC." (PMID 27517148, 2016). "The KRAS mutant SW48 cells have been derived artificially, and it is unlikely that both mutations co-exist in cancer cells that have not been genetically manipulated." (PMID 27187477, 2016). "In addition, oncogenes, such as KRAS, BRAF, and C-MYC, can stimulate NRF2 transcription and activation in cancer cells." (PMID 27703446, 2016). "Indeed, a recent phase II study of combination trastuzumab plus lapatinib in KRAS wt and HER2 IHC 2/3+ and FISH + cancers met its primary efficacy endpoint and reported a 32% response rate in patients with advanced, treatment refractory cancer." (PMID 26980732, 2016). "Other mutations among a panel of 39 cancer-related genes do not further add to performance over GNAS and KRAS." (PMID 27992432, 2016). "The remaining seven molecules had no connection with oncogenic KRas signaling in the cancer cell lines established in the literature." (PMID 27894102, 2016). "However, only three members, KRAS, NRAS and HRAS, are of paramount importance in the context of cancer development and clinical significance." (PMID 27276710, 2016). "Surprisingly, after the stimulation of cells with IL-1β or TNFα, after mitophagy induction or in cancer dependent on KRAS signaling, TBK1 is phosphorylated whereas IRF3 is not." (PMID 27538435, 2016). "In spite of the importance of KRas mutants in cancer biology, there are no reports to date on in-depth proteomic profiling of the surface of cancer cells expressing KRas mutants." (PMID 27894102, 2016). "In clear contrast to HME and MCF10A cells, Noxa levels did not depend on KRAS status in cancer cells and in line with this observation cell sensitivity was almost identical in each pair of isogenic cells." (PMID 26028667, 2015). "Although this approach has an immense potential, no successful therapy for treating KRAS-driven cancers has emerged recently." (PMID 26158412, 2015). "Recent studies have suggested that the KRAS-mutant cancer cell lines, including CRC could be divided into two groups based on their “KRAS-dependency”." (PMID 26439693, 2015). "In this setting, ADM and PanIN lesions never recover Mist1 expression, suggesting that KRAS signaling events permanently inhibit the Mist1 gene in a cancer setting." (PMID 26717480, 2015). "In fact, similar to our findings, pharmacologic targeting of B-Raf results in increased activity of c-Raf and a paradoxical increase in ERK phosphorylation and tumorigenesis in KRas-mutant cancers; though this is not the case with genetic deletion of B-Raf." (PMID 26030593, 2015). "In contrast to the observed survival, the weighted average of expected 5 year survival rate was higher for CIP2A high/KRAS mutant than for CIP2A low/KRAS mutant patient group, suggesting that high CIP2A expression is an indicator of poor prognosis in KRAS mutant cancers." (PMID 26278961, 2015).
cancer (continued). "Taken together, our results indicate that oncogenic KRAS proteins activate autophagy through up-regulation of the MEK/ERK pathway in non-cancer colon and CRC-derived cells, suggesting that autophagy plays an important role in KRAS-driven colorectal carcinogenesis." (PMID 26418750, 2015). "In many different human cancers, one of the HRAS, NRAS, or KRAS genes in the RAS family of small GTPases acquires an oncogenic mutation that renders the encoded protein constitutively GTP-bound and thereby active, which is well established to promote tumorigenesis." (PMID 25902334, 2015). "Moreover, given that KRAS and p16 are the two most commonly mutated genes in PDAC, and that RB dysfunction is also common in PDAC, KRC mice could be a useful GEMM for studying angiogenesis that reflects events in PDAC patients whose cancers exhibit a pro-angiogenic signature." (PMID 25762644, 2015). "Using publicly available chromatin binding data sets we observed binding of several transcriptional regulators which lie downstream of EGFR, KRAS, PI3K and EMT signalling pathways, providing tangible leads for future functional studies aiming to decipher the regulators of MCT2 in cancer." (PMID 26035357, 2015). "A key point for targeting cells stuck in S-phase is the specificity for KRas-driven cancer cells – in that these cancer cells do not arrest in G1 in response to either Gln deprivation or suppression of Gln utilization." (PMID 26682255, 2015). "As KRAS expression leads to increased replication stress, the effect of combined MK2 and Chk1 inhibition likely take advantage of the addiction of hyper-replicating cancer cells to checkpoint signaling." (PMID 26295265, 2015). "According to these estimates, each cancer cell will generate ≥ 230 (i.e. ~109) of KRAS-independent offspring." (PMID 26158412, 2015). "The Kirsten rat sarcoma viral oncogene homolog (KRAS) protein is an important signaling mediator in the epidermal growth factor receptor (EGFR) pathway, which regulates cell growth and is commonly targeted in cancer therapy." (PMID 25823645, 2015). "Despite continuous efforts, no successful therapy targeting KRAS has been developed and it remains an elusive target for cancer therapy." (PMID 26418750, 2015). "Cancer cells with wild-type KRAS and BRAF show clear changes upon erlotinib treatment, whereas BRAF- and KRAS-mutated cancer cells display a limited change or no significant changes, respectively." (PMID 26168967, 2015). "Furthermore, the largest effect is observed in lipid droplets of cancer cells harbouring wild-type BRAF and KRAS that were treated with erlotinib." (PMID 26168967, 2015). "Despite the presence of mutant KRAS, our findings suggest that cancer cells are not sensitized to SM83/CPT treatment." (PMID 26028667, 2015).
cancer (continued). "Although there is little evidence demonstrating the involvement of mutated KRAS in MDB development, we were able to reproduce a cancer model with features of pediatric MDB due to the specific expression of KRASG12D in ptf1a-expressing tissues." (PMID 24878567, 2014). "The possibility that in KRAS and BRAF mutant cancer cells differential signalling mechanisms that involve MEK, supported the mutual exclusivity of these two mutations, lead to the target-specific cancer therapeutics in the form of monoclonal antibodies against EGFR and VEGF receptors." (PMID 25361007, 2014). "Overall these findings substantiate the importance of GLI as a target in cancers with activated GLI and/or oncogenic KRAS/BRAF signaling, and that inhibition of GLI-dependent transcription by a specific small molecule inhibitor can have profound effects on cell survival." (PMID 24962990, 2014). "To determine if KRAS amplification had functional consequence in cancer, we queried Project Achilles and found that most cancer cell lines displayed a negative shRNA score in response to KRAS shRNA infection." (PMID 24874471, 2014). "When using SNVs only, most such genes were known cancer genes, such as U2AF1, IDH1, and DNMT3A in LAML (FLT3 SNVs cluster within five amino acids), AKT1 and KRAS in BRCA, BRAF and KRAS in COADREAD, IDH1 and PARG (poly (ADP-ribose) glycohydrolase) in GBM, and KRAS in UCEC." (PMID 25348067, 2014). "Authors suggest as this evidence may create the basis for several hypotheses explaining mechanisms by which combinations of KRAS and ALK status might exist through clonal cancer evolution." (PMID 24691006, 2014). "Furthermore, it would be of extreme benefit to the fight against cancer if these results were comparable with the outcomes of anti-EGFR monoclonal antibody and KRAS status in CRC." (PMID 24283603, 2013). "Among nine cancer-associated mutations that determine sensitivity to ATRA (Notch 1, BCR_ABL, KIT, FLT3, APC, TET2, K-ras, ALK, MLL_AFF1), KRAS, APC, and KIT mutations are associated with resistance to ATRA (only K-ras is shown)." (PMID 23982413, 2013). "Interestingly, all cell lines that were sensitive to SREBP ablation show mutations in a component of the PI3-kinase pathway (PTEN, PIK3CA or KRAS; COSMIC cancer cell line project), while the insensitive SKBR3 cell line is wild type for these genes." (PMID 24280005, 2013). "IGF2BPs could be exploited in cancer through their influence on classical oncogenes, in particular MYC and KRAS." (PMID 23069990, 2013). "None of the cancers in this study reached the conventional threshold for CIMP positivity 21, although we did observe the reported association between KRAS mutation and a 'CIMP-low' phenotype 10." (PMID 23096130, 2013). "Rational candidate based approaches that target key pathways required during the process of tumorigenesis for KRAS mutant cancers have not been exhaustive." (PMID 22654667, 2012).
cancer (continued). "Knocking-down KRAS in DLD-1G13D cells resulted in cells more resistant to oxaliplatin, but not to irinotecan, and 5FU, standard chemotherapeutic agents for CRC, and not to doxorubicin, broad spectrum chemotherapeutic agent for other major cancers." (PMID 23209813, 2012). "This also opens up the potential to target mutant KRAS-driven cancers, which thus far have no effective therapeutics." (PMID 23202889, 2012). "The rates of KRAS mutations were comparable in CIMP-high (35.3%) and CIMP-low/negative carcinomas (34.1%)." (PMID 21827707, 2011). "To gain further insight into the role of overexpressed KRAS in cancer cell growth, we analyzed the activation of p44/42 MAP kinase and AKT, which are pivotal molecules in the MAP kinase cascade and PI3K signaling pathways that are downstream of KRAS." (PMID 19545448, 2009). "This raises the possibility that KRAS and BRAF mutant cancer cells might be differentially dependent on signalling mechanisms that involve MEK." (PMID 19018267, 2008). "In addition to covalently suppressing mutant KRAS proteins, the degradation of the oncogene KRAS using the proteolysis-targeting chimeras (PROTAC) has emerged as an alternative approach to KRAS-mutant cancers." (PMID 41362725, 2026). "By demonstrating the potential of both ADT-007 and the 3D BEST model, we lay the groundwork for future investigations that could ultimately lead to more effective and personalized treatment strategies for patients with KRAS-mutant CRC and other RAS-driven cancers." (PMID 41008802, 2025). "These experiments showed that heterozygous expression of Rnpc3 is sufficient to markedly restrict the growth and proliferation of cancers driven by a variety of pro-proliferative, pro-survival pathways (KRAS/MAPK and STAT3), without any impact on healthy tissues." (PMID 40624356, 2025). "Embelin cotargets SHP2 to disrupt the SHP2/GRB2/SOS complex, inhibiting cancer‐related signaling pathways such as MAPK, (PI3K)/AKT pathway, and XIAP to induce apoptosis signaling pathway, respectively, leading to synthetic lethality in KRAS‐mutant NSCLC cells both in vivo and in vitro." (PMID 39992860, 2025). "Non-CRC gastrointestinal KRAS G12C cancers (n = 17) had an ORR of 33.5%." (PMID 41309533, 2025). "KRAS(G12V) expression was dose dependent and, for subsequent autophagy analysis, we systematically adjusted the concentration and fine-tuned the induction duration to achieve an expression level comparable to that of endogenous RAS in various cancer cell lines." (PMID 40055523, 2025). "Together, our data indicate that sorafenib can effectively prevent the emergence of resistance in cancer cells addicted to mutant EGFR, but not in cells addicted to other driver mutations frequently found in NSCLC, such as those involving the oncogenes KRAS and ALK." (PMID 40846697, 2025). "Second, although we selected cancer cell lines that recapitulate the two most common CRC and PDAC subtypes, KRAS G12D and G12V, these cancer cells could partially explain the spectra of KRAS‐activating mutations and their combination with other driver genes present in individual tumors." (PMID 40013338, 2025). "Compared to current HCC therapies that offer only minimal improvements in overall survival, niclosamide offers promise as a cancer multitool compound due to its ability to decrease the AR/AR-SV protein and prevent rebound oncogenic signaling through its activity against NF-κB, STAT3, and KRAS." (PMID 40805231, 2025).